LATS2 (large tumor suppressor kinase 2)
Diseases named in the same sentence as LATS2 in open-access papers (continued):
Sharing a sentence is not in itself a finding about the gene and the disease.
myocardial infarction (6 papers, 2019 to 2025). Gross necrosis of the myocardium, as a result of interruption of the blood supply to the area, as in coronary thrombosis. "Since Lats2 activity may trigger mitochondrial dysfunction, a key pathogenic factor in acute myocardial infarction (AMI), this study sought to investigate whether Lats2 deletion confers cardioprotection in AMI." (PMID 37497006, 2023). "In summary, miR-93 directly inhibits the Hippo pathway activity by targeting LATS2, thereby improving cardiac function after myocardial infarction." (PMID 38698813, 2024). "Consistent with the observations in Mst1 and Mst2 mouse models, genetic inhibition of Lats2 using a dominant negative mutant attenuated apoptosis and improved the phenotype following myocardial infarction in mice." (PMID 31328787, 2019). "The protective effects of downregulating circFASTKD1 following myocardial infarction can be explained by our findings that circFASTKD1 sponges miR-106a and thus de-represses LATS1 and LATS2." (PMID 33411690, 2020).
diabetes (5 papers, 2017 to 2025). "While control animals showed a progressive development of diabetes (hyperglycemia, severely impaired glucose tolerance, impaired insulin secretion), β cell LATS2-deficient mice showed milder changes in diabetes development induced by low doses of STZ." (PMID 35054822, 2022). "INS-1E cells and cells derived from human pancreatic islets have been shown to be highly susceptible to LATS2 deficiency, resulting in improved viability, increased cell mass, and restoration of insulin secretion, which combine to reduce the development of diabetes." (PMID 35054822, 2022). "As LATS2 depletion protected from β-cell apoptosis under multiple diabetic conditions in vitro, we hypothesized that LATS2 deficiency may protect from diabetes development in vivo." (PMID 34389720, 2021). "The arrest of the mTORC1 pathway was revealed by the blocking of β cell apoptosis, which clearly showed that the pro-apoptotic effect of LATS2 is mTORC1-dependent and is over-activated by LATS2 in diabetes in INS-1E cells and human pancreatic islets." (PMID 35054822, 2022). "The interpretation of LATS2 action in diabetes and apoptosis has been confronted with an explanation of the role and interaction of mTOR and autophages in these processes." (PMID 35054822, 2022). "Our data reveal an important role for LATS2 in pancreatic β-cell turnover and suggest LATS2 as a potential therapeutic target to improve pancreatic β-cell survival and function in diabetes." (PMID 34389720, 2021). "In the future, the important function of LATS2 in its circular regulation of autophagy ending in β-cell failure makes it a promising target for β-cell-directed diabetes therapy." (PMID 34470573, 2021). "LATS2 deficiency in β-cells and primary isolated human islets as well as β-cell specific LATS2 ablation in mice improves β-cell viability, insulin secretion and β-cell mass and ameliorates diabetes development." (PMID 34389720, 2021). "To further verify this result, we conducted western blot analysis and revealed that Ras-related associated with diabetes (RRAD) and Large tumor suppressor 2 (LATS2) protein levels was also increased in si-DUXAP10 transfected cells." (PMID 28029651, 2017). "Unfortunately, it should also be remembered that theoretically, the inhibition of MST1 will not stop the Hippo pathway, and cell stress factors (those that lead to diabetes) may activate the second kinase of the LATS2 pathway (e.g., via Merlin)." (PMID 35054822, 2022). "To assess whether β-LATS2−/− might protect against β-cell injury and diabetes, we induced diabetes by multiple-low dose streptozotocin (MLD-STZ) injection in β-LATS2−/−, LATS2fl/fl, and Rip-Cre mice." (PMID 34389720, 2021). "Also, selective disruption of Lats2 in β cells in vivo restores normoglycemia, β-cell function and survival as well as the β-cell compensatory response in mouse models of diabetes." (PMID 34470573, 2021). "Using a multi-model approach, we have identified LATS2 as pro-apoptotic kinase whose abnormal activation led to impaired β-cell survival and function, while its depletion restored functional β-cell mass and protected against diabetes progression." (PMID 34389720, 2021). "Therefore, we further analyzed the LATS2-mTORC1 crosstalk and whether mTORC1 mediates the pro-apoptotic function of LATS2 in the context of diabetes." (PMID 34389720, 2021). "Blocking LATS2 could be a promising strategy to improve β-cell survival in diabetes." (PMID 34389720, 2021). "Studies of human β cells/pancreatic islets under experimentally induced diabetes have shown that the inhibitory effects of MST1 and LATS2, the major kinases of the Hippo pathway, exhibit high functional and anti-apoptotic efficacy." (PMID 35054822, 2022). "In vivo experiments were carried out on a mouse model with a β cell-specific LATS2 deletion (β-LATS2-/-) and the LATS2fl/fl control group with MLD-STZ experimentally induced diabetes." (PMID 35054822, 2022).
diabetes (continued). "Similarly, LATS2 ablation achieved by siRNA in β-cells can protect from both STZ and HFD-induced diabetes." (PMID 40707469, 2025). "Nevertheless, such a mechanism of action does not function in long-term stress (e.g., diabetes), the effect of which is the development of apoptosis through the activation of LATS2, mTORC1, which results in the implementation of defective autophagy." (PMID 35054822, 2022). "In conclusion, LATS2 may be a second therapeutic target alongside MST1, whose blockage of action may lead to improved function and increase β cell survival in diabetes." (PMID 35054822, 2022). "Altogether, our data show that β-cell-specific ablation of LATS2 diminished progressive hyperglycemia and improved glucose tolerance, insulin secretion, and β-cell mass in the MLD-STZ mouse model of β-cell destruction and diabetes." (PMID 34389720, 2021). "Taken together, these data suggest that the HFD induced LATS2 hyper-activation has a detrimental impact on β-cell viability, β-cell compensatory response and insulin secretion in the diet induced HFD model of β-cell decompensation and diabetes." (PMID 34389720, 2021).
oral squamous cell carcinoma (5 papers, 2020 to 2024). "For example, M2-sEVs enable complementary pairing of miRNA-31-5p and large tumor suppressor kinase 2 (LATS2)-encoding sequences in recipient oral squamous cell carcinoma (OSCC) cells." (PMID 35832790, 2022). "Therefore, the present study tried to investigate whether LATS2 promoter methylation was associated with oral squamous cell carcinoma (OSCC) in North Indian subjects." (PMID 32458634, 2020). "Moreover, miR-103a-3p regulates proliferation and apoptosis by targeting RCAN1 in oral squamous cell carcinoma (OSCC) cells, miR-103 promotes HCC growth by inhibiting AKAP12 or by promoting glucose metabolism function, and miR-103 promotes metastasis and EMT by inhibiting LATS2." (PMID 36273122, 2022).
acute myeloid leukemia (4 papers, 2011 to 2021). Acute myeloid leukemia (AML) is a group of neoplasms arising from precursor cells committed to the myeloid cell-line differentiation. "In acute myeloid leukemia (AML), augmented expression of the LATS2 gene was identified in 32 de novo AML subjects, indicating that LATS2 may be correlated with leukemogenesis." (PMID 33924049, 2021). "It is worth noting that while LATS2 promoter hypermethylation had been reported in another cancer with frequent IDH mutations, namely IDH-mutant acute myeloid leukemia (AML), it did not downregulate LATS2 expression as it did in LGG, suggesting a different mechanism or role." (PMID 33195240, 2020).
cervical cancer (4 papers, 2011 to 2022). A primary or metastatic malignant neoplasm involving the cervix. "We firstly revealed that LATS2 as a tumor suppressor in cervical cancer and LATS2 overexpression promoted tumor cells apoptosis." (PMID 35454780, 2022). "Our study provided the first evidence that SFN and LATS2 overexpression enhanced the radiosensitivity of human cervical cancer cells in vitro." (PMID 35454780, 2022). "SFN treatment and LATS2 overexpression also inhibited cervical cancer survival after irradiation by suppressing Rad51 and MDC1 nucleus recruitment and DNA damage repair." (PMID 35454780, 2022). "In this study, we identified SFN as radiotherapy sensitizer of cervical cancer cells and LATS2 as a novel downstream target gene of SFN." (PMID 35454780, 2022). "We identified SFN as cervical cancer cells radiotherapy sensitizer and LATS2 served as a downstream target of SFN treatment." (PMID 35454780, 2022). "Firstly, we discovered that LATS2 overexpression suppressed the cervical cancer cells survival after irradiation and LATS2 knockdown enhanced the colony formation compared with the control group." (PMID 35454780, 2022). "LncPVT1 can also epigenetically downregulate large tumor suppressor kinase 2 (LATS2) in NSCLC via recruitment of EZH2 and methylation of the LATS2 promoter, similar to the mechanism in cervical cancer." (PMID 31508377, 2019). "To investigate whether LATS2 alters the biological characteristics of cervical cancer cells, we attempted to overexpress LATS2 in the HPV (+) SiHa cells line and the HPV (−) C33A cells line by transfecting cells with plasmids PcDNA3.1-LATS2." (PMID 35454780, 2022). "SFN increased the protein expression of LATS2 and promoted apoptosis of cervical cancer cells." (PMID 35454780, 2022). "SFN served as the agonist of LATS2 and promoted cervical cancer radiosensitivity, and LATS2 might act as a radiotherapy-sensitive marker in the future." (PMID 35454780, 2022). "Our results indicated that SFN could enhance the expression of LATS2 and exert irradiation sensitization in cervical cancer cells by suppressing DNA double-strand break repair, specifically by inhibiting Rad51 and MDC1 nuclear accumulation." (PMID 35454780, 2022). "Overexpressed LATS2 decreased the cellular survival rate of cervical cancer cells." (PMID 35454780, 2022). "Thus, we further verified the impact of SFN treatment on LATS2 expression in cervical cancer cells." (PMID 35454780, 2022). "We found that the recruitment of MDC1 in the nucleus was blocked upon LATS2 overexpression and SFN treatment, resulting in the impaired formation of Rad51 foci under ionizing radiation in cervical cancer cells." (PMID 35454780, 2022). "We also identified the regulatory role for LATS2 in HR repair and our data suggested that SFN could be an appealing target to therapeutically induce DNA breaks and increase the sensitivity of cervical cancer cells to radiotherapy." (PMID 35454780, 2022). "LATS2 mRNA was also significantly upregulated when SFN treated, and no study has illustrated the role of LATS2 in cervical cancer." (PMID 35454780, 2022). "Additionally, SFN treatment and LATS2 overexpression prevented MDC1 and Rad51 from accumulating in the nucleus in cervical cancer cells after being exposed to ionized radiation." (PMID 35454780, 2022). "However, the role of LATS2 in tumor suppression has not been fully elucidated in cervical cancer." (PMID 35454780, 2022). "On performing immunoblot analysis of LATS2, we did not detect LATS2 in AGS cells, in contrast to the other gastric cell line MKN-74 and the cervix cancer cell line HeLa." (PMID 22027184, 2011).
gallbladder cancer (4 papers, 2018 to 2021). "Long noncoding RNA MEG3 regulates LATS2 by promoting the ubiquitination of EZH2 and inhibits proliferation and invasion in gallbladder cancer." (PMID 34789260, 2021). "In Gallbladder cancer, lncRNA MEG3 performs functions by regulating the stability of EZH2 to regulate the downstream target gene LATS2 and thereby inhibits invasion and proliferation." (PMID 34131399, 2021).
Insulin resistance (4 papers, 2016 to 2024). Increased resistance towards insulin, that is, diminished effectiveness of insulin in reducing blood glucose levels. "Under chronic metabolic stress (e.g., insulin resistance), LATS2 fosters activation of MTORC1, which then contributes to autophagy inhibition, subsequent accumulation of LATS2 and induction of apoptotic signaling." (PMID 34470573, 2021).
melanoma (4 papers, 2022 to 2025). A malignant, usually aggressive tumor composed of atypical, neoplastic melanocytes. "However, the mechanisms underlying LATS2 expression regulation, particularly by non-coding RNAs such as micro RNAs (microRNAs), remain elucidated in melanoma." (PMID 39866229, 2025). "Targeting the exosomal miR-424-5p/LATS2 axis emerges as a potential therapeutic strategy for melanoma." (PMID 39866229, 2025). "Large tumor suppressor kinase 2 (LATS2) is recognized as a critical regulator in the progression of various cancers, including prostate, pancreatic, and melanoma." (PMID 39866229, 2025). "In melanoma, LATS2 has been shown to inhibit cell growth and metastasis, and its downregulation is associated with poor prognosis." (PMID 39866229, 2025). "Melanoma cell-derived exosomal miR-424-5p promotes angiogenesis by targeting LATS2, contributing to melanoma progression." (PMID 39866229, 2025). "Our findings suggest that targeting the exosomal miR-424-5p/LATS2 axis could represent a potential therapeutic strategy for melanoma." (PMID 39866229, 2025). "Targeting the exosomal miR-424-5p/LATS2 axis could be a potential therapeutic strategy for melanoma." (PMID 39866229, 2025). "Notably, the downregulation of LATS2 in melanoma cells stimulates cell growth, suggesting its potential role as a tumor suppressor in melanoma development." (PMID 39866229, 2025). "Further, the overexpression of LATS2 in amyloid-deficient melanoma cells does not block the effects of rPMEL amyloid fibrils on CTGF expression, indicating that increasing the level of LATS2 is not sufficient to shut down mechanotransduction exerted by PMEL amyloid fibrils." (PMID 38199984, 2024). "To this end, we treated proliferative M000921 and M010817 patient-derived melanoma cells with either recombinant human TGFβ or with recombinant murine Wnt-3a, or we knocked down LATS1 and LATS2 to induce the transcriptional activity of YAP/TAZ." (PMID 34819356, 2022).
nasopharyngeal carcinoma (4 papers, 2010 to 2024). A carcinoma arising from the nasopharyngeal epithelium. "The association of LATS2 protein expression with the clinicopathological characteristics and the prognosis of nasopharyngeal carcinoma were subsequently assessed." (PMID 20932276, 2010). "The LATS protein was also up-regulated in nasopharyngeal cancer, and siRNA-targeting LATS2 inhibited tumor progression." (PMID 38368446, 2024). "For instance, cell proliferation was reduced and apoptosis was enhanced by ISL in nasopharyngeal carcinoma via affecting the miR-32/LATS2/Wnt axis." (PMID 37020694, 2023). "Using quantitative real time PCR and immunoblotting, the expression of LATS2 was detected in nasopharyngeal carcinoma cell lines and in the immortalized nasopharyngeal epithelial cell line NP69." (PMID 20932276, 2010). "LATS2 overexpression was a significant, independent prognosis predictor (P = 0.037) in nasopharyngeal carcinoma patients." (PMID 20932276, 2010). "Functional studies showed that the suppression of LATS2 expression in nasopharyngeal carcinoma (5-8F and CNE2) cell lines by using specific small interfering (siRNA) resulted in the inhibition of growth, induction of apoptosis and S-phase cell cycle increase." (PMID 20932276, 2010). "Using immunohistochemistry, we analyzed LATS2 protein expression in 220 nasopharyngeal carcinoma cases." (PMID 20932276, 2010). "In this study, we aimed to investigate the expression pattern of LATS2 and its clinicopathological involvement in nasopharyngeal carcinoma to understand its effect on cell survival." (PMID 20932276, 2010). "Our results indicate that LATS2 might play a role in the tumorigenesis of nasopharyngeal carcinoma by promoting the growth of nasopharyngeal carcinoma cells." (PMID 20932276, 2010). "LATS2 protein was detected in 178 of 220 (80.91%) cases of nasopharyngeal carcinoma." (PMID 20932276, 2010). "However, the role of LATS2 in nasopharyngeal carcinoma has not been investigated." (PMID 20932276, 2010).
sarcoma (4 papers, 2018 to 2021). A usually aggressive malignant neoplasm of the soft tissue or bone. "Loss of expression of LATS1 and LATS2 was noted in 8% (9/113) of sarcomas." (PMID 30167083, 2018). "Within these TAZ/YAP activated sarcomas, 47% (54/114) demonstrated loss of MST1 expression, 26% (30/117) demonstrated loss of MST2 expression, 19% (22/113) of the sarcomas demonstrated loss of LATS1 expression, and 27% (32/117) of the sarcomas demonstrated loss of LATS2 expression." (PMID 30167083, 2018). "Studies show that promoter methylation of Lats1 and Lats2 is common in schwannomas (17% and 30%, respectively), while promoter methylation of Mst1 and Mst2 has been detected in 37% and 17% of sarcomas, respectively." (PMID 32960816, 2020). "Approximately 49% of sarcomas (73/148) demonstrate loss of MST1, 31% of sarcomas (46/148) demonstrate loss of MST2, 23% of sarcomas (34/148) demonstrate loss of LATS1 expression, and 29% of sarcomas (45/153) demonstrate loss of LATS2." (PMID 30167083, 2018). "By immunohistochemistry, TAZ/YAP activated clinical sarcoma samples demonstrated loss of MST1 (47%), MST2 (26%), LATS1 (19%), and LATS2 (27%)." (PMID 30167083, 2018). "Evaluation of 259 sarcomas in The Cancer Genome Atlas demonstrated a mutation rate ranging from 0% for MST2 and LATS1 to 0.8% for LATS2." (PMID 30167083, 2018). "Alterations in various effectors of the Hippo signaling cascade such as YAP1, LATS2 or SAV1 copy number variations have recently been described in a variety of sarcoma subtypes and point to a major role of aberrant Hippo signals in different soft tissue malignancies." (PMID 31873172, 2019). "TSA promoted an increase of expression of LATS2 in 1 of 12 sarcoma cell lines (8%)." (PMID 30167083, 2018). "Approximately 8% of sarcoma cell lines demonstrated loss of expression of LATS1 at the RNA level, while no cell lines demonstrated loss of expression of LATS2 at the RNA level." (PMID 30167083, 2018). "The finding that LATS2 expression decreased with MG132 treatment in some sarcoma cell lines suggests that treatment with proteosomal inhibitors for sarcomas with decreased MST2 expression may not be effective." (PMID 30167083, 2018). "In silico analysis demonstrated that 0.8% of sarcomas demonstrated genomic deletions of MST2 and LATS2 combined, indicating that deletions are not a common mechanism by which loss of expression of the Hippo kinases occurs." (PMID 30167083, 2018).
schwannoma (4 papers, 2020 to 2026). A benign, usually encapsulated slow growing tumor composed of Schwann cells. "Lats1 or Lats2 loss of heterozygosity in H7;Lats1/2mut3 mice is required for schwannoma development." (PMID 32960816, 2020). "Our results show that loss of heterozygosity of the residual WT Lats1 or Lats2 allele in H7;Lats1/2mut3 mice is required for schwannoma development." (PMID 32960816, 2020). "We confirmed increased LATS2 expression and sustained Hippo pathway activation (pYAP) in Merlin-deficient schwannoma after MLN3651 treatment for 72 h, suggesting that MLN3651 inhibits CRL4-DCAF1 activity in Merlin-deficient cells." (PMID 32629964, 2020). "Firstly, complete loss of both Lats1 and Lats2 in the Hoxb7+ lineage resulted in multiple schwannoma formation." (PMID 32960816, 2020). "Whilst we did not see a consistent increase in pYAP at the time points tested in meningioma, we were able to show that MLN3651 treatment of Merlin-deficient schwannoma increased both LATS2 and pYAP, demonstrating that MLN3651 is able to activate the Hippo pathway." (PMID 32629964, 2020). "Only 2% and 1% of human schwannomas carry Lats1 and Lats2 mutations, respectively, and no Mst1/2 mutation has been reported in human cancer." (PMID 32960816, 2020). "Other recurrently altered genes reported in schwannomas include LATS1, LATS2, ARID1A, ARID1B and DDR1." (PMID 41300852, 2025).